TRPM8 (transient receptor potential cation channel subfamily M member 8)
Diseases named in the same sentence as TRPM8 in open-access papers (continued):
Sharing a sentence is not in itself a finding about the gene and the disease.
neuropathy (13 papers, 2010 to 2025). A disorder affecting the nervous system that manifests with pain, tingling, numbness, and/or muscle weakness. "On the other hand, the cold allodynia associated to oxaliplatin-induced painful neuropathy has been correlated with TRPM8 expression and function, while other studies indicate that TRPM8 is implicated in cold allodynia after inflammation or nerve injury." (PMID 33673444, 2021). "In summary, we found that aberrant TRPM8 activity in sensory neurons was a crucial and a very early effect of oxaliplatin-treatment, an effect that seems to be linked to oxaliplatin-induced neuropathy and that may be targeted pharmacologically to alleviate oxaliplatin-induced pain." (PMID 34066977, 2021). "We conclude that targeting TRPM8 early after oxaliplatin treatment may ameliorate oxaliplatin-induced acute pain and may thus reduce the risk of patients developing a strong long-term neuropathy." (PMID 34066977, 2021). "Previous studies have shown that TRPM8 is involved in oxaliplatin-induced cold hypersensitivity, with TRPM8 expression elevated in oxaliplatin neuropathy." (PMID 38892000, 2024). "Recent work has revealed that TRPM8 also contributes to the development of platinum-induced neuropathy, where TRPM8 is observed to be upregulated after treatment with platinum." (PMID 35361751, 2022). "TRPM8 has also been involved in the painful hypersensitivity that is a worrying symptom in inflammation and neuropathy." (PMID 31703254, 2019). "Lastly, small molecule antagonists are efficacious in animal models of neuropathy and overactive bladder, thus supporting a potential therapeutic benefit of TRPM8 antagonists." (PMID 25203266, 2014). "Genetic ablation of TRPM8 in mice abolishes cold-evoked behaviors after peripheral inflammation or nerve injury and in models of chemotherapy-induced neuropathy." (PMID 25203266, 2014). "This is the first study to describe sensitization of TRPV1 and TRPA1 and/or TRPM8 in a model of oxaliplatin induced neuropathy, the role of cAMP in mediating the sensitization, and the effectiveness of a CB2 agonist in mitigating it." (PMID 21106058, 2010). "Given the inhibitory activity of compound 23 and the antinociceptive effects of TRPM8 antagonists described in models of oxaliplatin (OXP)‐induced neuropathy, we conducted a behavioral experiment in mice to assess the antinociceptive effects of compound 23 after repeated oxaliplatin administration." (PMID 40123199, 2025). "There was no report about direct activation of TRPM8 channels by oxaliplatin but TRPM8 might play a role in cold sensing in oxaliplatin-induced neuropathy by the observation with TRPM8 knock out animals." (PMID 25928068, 2015). "We have also examined whether menthol induces similar analgesic effects in a rodent model of neuropathy, and finally, the systemic effects of a novel TRPM8 agonist, M8-Ag, on cold sensitivity in sham-operated and SNL rats." (PMID 25083927, 2014). "Moreover, an increase of TRPM8 expression in different animal models such as neuropathy induced by oxaliplatin and by streptozotocin-induced diabetes is documented, confirming its role in the somatic sensory nervous system response and underlining its function in pain management." (PMID 31703254, 2019). "Moreover, TRPM8 antagonist was also used in a chronic pain model, such as neuropathy." (PMID 31703254, 2019). "The effect of Goshajinkigan on neuropathy through inhibition or stimulation of TRPA1, TRPM8, and TRPV1 channels in oxaliplatin-induced neuropathy rat model was recently investigated." (PMID 29326595, 2017). "Systemic TRPM8 agonists might be beneficial in neuropathy without affecting normal cold sensitivity." (PMID 25083927, 2014). "Therefore the major role between TRPM8 and TRPA1 for cold sensing in oxaliplatin-induced neuropathy is not clearly identified and further studies are needed." (PMID 25928068, 2015).
pancreatic adenocarcinoma (12 papers, 2012 to 2024). "In pancreatic adenocarcinoma, TRPM8 channels are associated with TRPM8 channel-associated factors 1 and 2 (TCAF1 and TCAF2)." (PMID 37033630, 2023). "The aberrant expression of TRPM8 in pancreatic adenocarcinoma is associated with a function role." (PMID 24278689, 2012). "On the contrary, TRPM8 can prevent gene-induced senescence of cancer cells, which means that it is beneficial to the proliferation and anti-senescence of pancreatic adenocarcinoma cells and promotes the progression of the disease." (PMID 35573736, 2022). "Pancreatic adenocarcinoma (PC) cell lines overexpressed TRPM8 channels, and this fact has been correlated to advanced TNM, vast tumor size, and distant metastasis." (PMID 36844925, 2022). "TRPM8 protein was found to be upregulated in human pancreatic adenocarcinoma cell lines and tissues." (PMID 32182937, 2020). "Statistical analysis indicates that the aberrant over-expression of TRPM8 in pancreatic adenocarcinoma significantly correlates with tumor size and tumor stages." (PMID 26512697, 2015). "Immunohistochemical analysis demonstrates that TRPM8 is expressed at either moderate or high levels in the majority of pancreatic adenocarcinoma specimens." (PMID 26512697, 2015). "Translation of developmental regulators of exocrine pancreatic development in zebrafish has led to discovery of TRPM7 and its subfamily member TRPM8 in pancreatic adenocarcinoma." (PMID 24861976, 2014). "In the pancreatic adenocarcinoma cell lines that express relatively high levels of TRPM8, short hairpin RNA-mediated interference of TRPM8 expression impaired their ability of invasion." (PMID 24861976, 2014). "Recent studies indicate that TRPM8 channels are aberrantly expressed and required for cellular proliferation in pancreatic adenocarcinoma." (PMID 24861976, 2014). "The objectives of this study are to examine the expression of TRPM8 in various histopathological types of pancreatic tissues, determine its clinical significance in pancreatic adenocarcinoma, and investigate its functional role in cancer cells invasion." (PMID 24861976, 2014). "In the majority of specimens of pancreatic adenocarcinoma, the expression levels of TRPM8 are relatively moderate or high." (PMID 24861976, 2014). "In pancreatic adenocarcinoma cell lines, short hairpin RNA-mediated silencing of TRPM8 impaired cancer cells invasion." (PMID 24861976, 2014). "Our data indicate TRPM8 channels are aberrantly over-expressed in the majority of specimens of pancreatic adenocarcinoma, and the expression levels of TRPM8 positively correlate with tumor size and stage." (PMID 24861976, 2014). "In human pancreatic adenocarcinoma cell lines and in a few specimens of pancreatic adenocarcinoma tissues examined, expression of TRPM8 is consistently elevated." (PMID 24861976, 2014). "In this study, we aimed to examine the expression of TRPM8 in normal and pathological pancreatic tissues, explore the clinical significance of TRPM8 in pancreatic adenocarcinoma, and determine its role in cancer cells invasion." (PMID 24861976, 2014). "In the majority of pancreatic adenocarcinoma, TRPM8 is expressed at moderate or high levels, and anti-TRPM8 immunoreactivity positively correlates with the primary tumor size and stage." (PMID 24861976, 2014). "The percent coverage ± standard error for expression of TRPM8 in pancreatic adenocarcinoma with respect to the intensity and the tumor stage." (PMID 24861976, 2014). "A positive correlation is demonstrated in pancreatic adenocarcinoma between the expression levels of TRPM8 and tumor size/stages." (PMID 24861976, 2014). "Taken together, the TRPM8 channel is required for cellular proliferation in pancreatic adenocarcinoma by preventing cell cycle arrest and replicative senescence." (PMID 24278689, 2012).
pancreatic adenocarcinoma (continued). "In a panel of seven human pancreatic adenocarcinoma cell lines, expression of TRPM8 is consistently up-regulated, as determined by real-time polymerase chain reaction and compared to the immortalized pancreatic ductal epithelia." (PMID 24278689, 2012). "The aberrant over-expression and proliferative roles of the TRPM7 and TRPM8 ion channels in pancreatic adenocarcinoma suggest a unique opportunity of their development as clinical biomarkers and therapeutic targets." (PMID 24278689, 2012). "The novel findings of Trpm7 ion channel in the growth control of exocrine pancreas in zebrafish prompted discovery of the aberrant expression as well as the proliferative and migratory roles of TRPM7 and TRPM8 channels in human pancreatic adenocarcinoma." (PMID 24278689, 2012). "Analysis of human pancreatic adenocarcinoma tissues by immunohistochemistry using specific anti-TRPM8 antibodies shows that TRPM8 is aberrantly expressed." (PMID 24278689, 2012). "In addition to being activated by their activators, TRPM2, TRPM4, and TRPM5 can also be triggered by the influx of Ca2+ to participate in membrane depolarization, and TRPM2, TRPM7, and TRPM8 are involved in the progression of pancreatic adenocarcinoma." (PMID 35573736, 2022). "Furthermore, it was shown that TRPM8 is required for proliferation of the pancreatic adenocarcinoma cell lines, PANC-1 and BxPC-3, due to the cell cycle arrest in the G0/G1 phase." (PMID 32182937, 2020). "Furthermore, we suggest that TRPM8 channels can be potentially developed as a clinical biomarker and therapeutic target in pancreatic adenocarcinoma." (PMID 24861976, 2014). "Moreover, we have demonstrated the novel roles of the human orthologue TRPM7 and its sub-family member TRPM8 in pancreatic adenocarcinoma." (PMID 24278689, 2012). "We propose a working model that will form the basis for testing our hypotheses regarding the signaling mechanisms that mediate the proliferative and prosurvival effects of TRPM8 in pancreatic adenocarcinoma by using cultured cells and animal models." (PMID 24278689, 2012). "In attempt to test the hypothesis that deregulated expression and/or activities of developmental regulators contributes to carcinogenesis, we have discovered that TRPM7 and TRPM8 are aberrantly overexpressed in pancreatic adenocarcinoma and required for proliferation of the cancer cells." (PMID 24278689, 2012). "Aberrant expression of TRPM8 has been reported in neoplastic tissues, some of which include prostate carcinoma, breast adenocarcinoma, lung cancer, colorectal cancer, melanoma, urinary bladder cancer, neuroblastoma, neuroendocrine tumor, and in the most recent finding pancreatic adenocarcinoma." (PMID 24278689, 2012). "In pancreatic adenocarcinoma PANC-1 and BxPC-3 cell lines, silencing TRPM8 reduced cell proliferation and showed impaired cell cycle progression, causing cells to arrest in the G1 phase and, hence, decreasing the number of cells entering S phase." (PMID 36844925, 2022). "Studies have shown that high TRPM8 expression was significantly correlated with large tumor size, advanced TNM and distant metastasis in pancreatic adenocarcinoma." (PMID 36371178, 2022). "Pancreatic adenocarcinoma cell lines (BxPC-3 and MIA PaCa-2) incubated with short hairpin RNA (shRNA)-mediated silencing of TRPM8 demonstrated reduced their ability to invade." (PMID 26512697, 2015). "In the pancreatic adenocarcinoma cell lines, BxPC-3 and PANC-1, small interfering RNA (siRNA)-mediated silencing of TRPM8 reduced cellular proliferation, as determined by MTS assay and counting cells." (PMID 26512697, 2015). "Therefore, immense potential exists for TRPM7 and TRPM8 channels to be developed as clinically useful biomarkers and valid therapeutic targets with the hope of accomplishing personalized therapy for patients with pancreatic adenocarcinoma and other malignant diseases." (PMID 24278689, 2012).
pancreatic adenocarcinoma (continued). "As a potential therapeutic approach in pancreatic adenocarcinoma, we can target the TRPM7 and TRPM8 ion channels via chemical and/or genetic modulation of their channel activities and their associated signaling pathways." (PMID 24278689, 2012). "Importantly, in the case of human pathological pancreatic adenocarcinoma, TRPM7 and TRPM8 are overexpressed and are necessary biomarkers for cancer cell proliferation." (PMID 35573736, 2022). "Initial studies demonstrated that TRPM8 is over-expressed in pancreatic adenocarcinoma cell lines and tissues, as compared to non-cancerous pancreatic ductal epithelia and tissues." (PMID 26512697, 2015). "Analysis of genomic DNA in pancreatic adenocarcinoma cell lines by real-time PCR suggests that amplification of TRPM8 DNA is unlikely to be involved." (PMID 26512697, 2015). "However, in pancreatic adenocarcinoma cell lines (BxPC-3 and PANC-1), siRNA-mediated down-regulation of TRPM8 did not induce apoptotic cell death as determined by flow cytometric analysis." (PMID 26512697, 2015).
glioma (11 papers, 2017 to 2024). A benign or malignant brain and spinal cord tumor that arises from glial cells (astrocytes, oligodendrocytes, ependymal cells). "Four TRP melastatin subfamily members, TRPM2, TRPM3, TRPM7, and TRPM8, have been implicated in glioma cell growth, proliferation and migration." (PMID 33928077, 2021). "TRPM7 and TRPM8 have both been linked to glioma proliferation." (PMID 36768856, 2023). "Therefore, TRPM8 overexpression in high-grade glioma might be associated with the documented upregulation of AR in GBM." (PMID 33928077, 2021). "The mechanism proved that ionizing radiation activates and upregulates TRPM8 in glioma, thus confirming the direct and indirect interaction in controlling glioma migration." (PMID 38680092, 2024). "MAPK signaling pathways related to TRPM8 are closely related to the malignant phenotype of glioma, which also shows a vital role in the cell death of glioma." (PMID 38680092, 2024). "The transient receptor potential melastatin family member 8 (TRPM8), bone morphogenetic protein 2 (BMP2) and L1CAM are upregulated in GBMs compared to normal brain tissue and are associated with glioma cell proliferation, migration and invasion." (PMID 34910361, 2022). "TRPM8-mediated Ca2+ influx promotes glioma progression by activating Ca2+ activated K+ ion channels with large conductance." (PMID 35493463, 2022). "Here, we discuss the potential as biological markers of diagnosis and prognosis of TRPC6, TRPM8, TRPV4, or TRPV1/V2 being associated with glioma patient overall survival." (PMID 33928077, 2021). "TRPM8 agonists have been shown to increase the Kir4.1 mediated membrane conductances of glioma cells." (PMID 33928077, 2021). "The present study aimed to disclose further functions of TRPM8 in glioma biology in particular upon cell injury by ionizing radiation." (PMID 29221175, 2017). "In addition, TRPM8 is closely associated with the MAPK signaling pathway, upregulating the expression of ERK, Bcl-2, and cyclin D1 in glioma cells, which is beneficial to cell proliferation." (PMID 39633507, 2024). "One of the possible mechanisms through which TRPM8-mediated Ca2+ influx may affect cell migration in glioma is by the activation of the large-conductance Ca2+-activated K+ ion channels (BK channels)." (PMID 33928077, 2021). "For instance, mRNA encoding TRPC1, TRPC6, TRPM7, TRPM8, TRPV4, and TRPML2 appeared up-regulated in GBM tumor specimens in comparison with normal tissues and their expression was found to increase with glioma tumor grade with the highest mRNA level found in GBM patient samples." (PMID 33928077, 2021). "Among them, TRPM2 and TRPM3 would exert anti-tumorigenic effects, while TRPM7 and TRPM8 may contribute to glioma malignancy." (PMID 33928077, 2021). "Furthermore, a TRPM8 agonist increases cytosolic Ca2+, subsequently leading to activation of Ca2+-activated K+ channels that induce glioma cell migration." (PMID 34149360, 2021). "The expression level of TRPM8 is markedly correlated with the invasiveness of glioma cells." (PMID 34149360, 2021). "Moreover, the increased invasion rate of glioma is also related to TRPM8 overexpression." (PMID 38680092, 2024). "Finally, TRPM8 channel might also modulate proliferation by dynamically control glioma resting potentials levels, which are key regulator of cell cycle." (PMID 33928077, 2021). "Interestingly, BK overexpression was detected in human glioma cells and pharmacological inhibition of BK channels was shown to abolish the menthol-stimulated Ca2+ influx within the cell cytoplasm and cell migration suggesting a key role of TRPM8." (PMID 33928077, 2021). "There is a growing consensus that TRPV1, TRPV2, TRPM2, TRPM3, and TRML1 exert anti-tumorigenic properties in glioma, while TRPC1, TRPC6, TRPM7, TRPM8, and TRPML2 promote glioma growth and proliferation." (PMID 36768856, 2023).
glioma (continued). "Several TRP channels have been studied as potential biological markers of glioma progression and prognosis, including TRPC1, TRPC6, TRPM2, TRPM3, TRPM7, TRPM8, TRPV1/2." (PMID 36768856, 2023). "Specifically, TRPM2 and TRPM3 demonstrate anti-tumor effects in gliomas, while TRPM7 and TRPM8 may play a role in the malignant transformation of gliomas." (PMID 39633507, 2024). "This evidence suggests that TRPM8 might converge to a common HGF/SF and cMET, known to play a role in malignancy of solid tumors including glioma, signaling pathway leading to migration/invasion." (PMID 33928077, 2021). "Similarly to TRPM8, TRPV4 has been shown to positively correlate with glioma progression, since high levels of TRPV4 gene and protein expression were associated with a poorer patient prognosis." (PMID 33928077, 2021). "TRPM8 inhibition or knockdown was sufficient to impair the cell cycle resulting in apoptotic cell death that may be mediated by MAPK signaling, ERK, and BCL2 in human glioma cells." (PMID 36768856, 2023). "Thus, TRPM8 and TRPV4 may be currently considered promising biomarkers accompanying aggressiveness of glioma and signature of GBM while constituting potential therapeutic targets for future treatment options." (PMID 33928077, 2021).